AHR (aryl hydrocarbon receptor)
Diseases named in the same sentence as AHR in open-access papers (continued):
Sharing a sentence is not in itself a finding about the gene and the disease.
ZIKV infection (6 papers, 2021 to 2024). "Recent research indicates that ZIKV infection induces the activation of the aryl hydrocarbon receptor (AhR) through the production of Kyn, as observed in genome-wide transcriptional studies." (PMID 38680494, 2024). "Initially, the researchers found that ZIKV infection significantly impacts the AHR signaling pathway by RNA sequencing of ZIKA-infected human hepatocytes HepG2." (PMID 36829212, 2023). "Hence, it is conceivable that sustained AHR activation in women exposed to pollutants and living in impoverished conditions with degraded housing and malnutrition might increase their susceptibility to ZIKV infection and ZIKV congenital syndrome." (PMID 33746961, 2021). "As in Zika virus (ZIKV) infection, virus-activated AHR worked as a host factor for ZIKV replication and suppressed intrinsic immunity driven by the promyelocytic leukemia (PML) protein." (PMID 34668726, 2021). "After ZIKV infection, the expression of AHR downstream target genes CYP1A1 and CYP1B1 increased." (PMID 36829212, 2023). "ZIKV infection of NPCs and HepG2 cells was demonstrated to induce kynurenine (Kyn), a tryptophan-derived aryl hydrocarbon receptor (AHR) ligand typically produced during inflammation by the enzymatic activity of indoleamine 2,3-dioxygenase 1 and 2 and tryptophan 2,3-dioxygenase." (PMID 33807177, 2021). "In addition, it was found that ZIKV infection triggers AHR activation, limiting the production of IFN-I, involved in antiviral immunity and favoring viral replication in vitro." (PMID 33746961, 2021). "Indeed, AHR was identified as a key proviral factor for ZIKV infection." (PMID 33746961, 2021). "Furthermore, through animal experiments, the researchers thoroughly verified that two types of AHR antagonists could effectively improve the related symptoms induced by ZIKV infection and identified AHR as a host factor of ZIKV infection and a candidate target for antiviral therapy." (PMID 36829212, 2023).
acromegaly (5 papers, 2014 to 2024). Acromegaly is an acquired disorder related to excessive production of growth hormone (GH) and characterized by progressive somatic disfigurement (mainly involving the face and extremities) and systemic manifestations. "Germline rs2066853 AHR variant was found to be more frequent among acromegaly patients and associated with a more severe disease with larger invasive somatropinoma, and with resistance to somatostatin analogs treatment in patients living in polluted areas." (PMID 33281746, 2020). "Germline mutations in the aryl-hydrocarbon receptor (AHR) interacting protein (AIP) have been identified in familial forms of acromegaly." (PMID 25019383, 2014). "Moreover, aryl hydrocarbon receptor (AHR) polymorphism is associated with the development and progression of acromegaly." (PMID 37584889, 2024). "Interestingly, the AhR gene itself appears to contribute to severity of acromegaly as polymorphisms and variants in AhR have been associated with more aggressive disease." (PMID 27853917, 2017). "AIP and AHR proteins are both expressed in normal pituitary tissue, and our data are the first to show that, while they are poorly expressed in the normal thyroid, AHR is selectively overexpressed in acromegaly-related PTC." (PMID 25019383, 2014). "Unexpectedly, PTCs unassociated with acromegaly revealed a high AHR protein expression as well, which was particularly evident in the BRAF-mutated cases." (PMID 25019383, 2014). "This AHR overexpression in PTC (particularly in BRAF-mutated cases) irrespective of a patient's acromegaly status could reflect a close relationship between AHR and BRAF." (PMID 25019383, 2014). "Nevertheless, despite clear evidence of a potential role of AHR in somatotropinomas pathophysiology and clinical relevance, somatic AHR gene alterations in acromegaly patients have not been reported." (PMID 33281746, 2020). "AIP protein expression was similar in neoplastic and normal cells, while AHR protein was expressed more in PTCs carrying BRAF mutations than in normal tissue, irrespective of acromegaly status." (PMID 25019383, 2014). "With this in mind, we looked at whether the main genetic drivers of DTC (BRAF and RAS mutations) were important in acromegaly-related DTC too, and we assessed the expression in DTC of the key molecular drivers of acromegaly (AIP and AHR)." (PMID 25019383, 2014). "There was no any difference in AHR staining score between PTCs in patients with versus without acromegaly." (PMID 25019383, 2014). "Moreover, AIP expression was similar between neoplastic and normal tissue, while the aryl-hydrocarbon receptor (AHR) was expressed more in PTCs carrying BRAF mutations than in normal tissue, irrespective of acromegaly status." (PMID 32333269, 2020). "However, no somatic changes in AHR gene have been reported so far in acromegaly patients." (PMID 33281746, 2020). "Judging from our preliminary findings, it would now seem reasonable to postulate an integrated model in which acromegaly would facilitate the acquisition of the somatic genetic drivers responsible for PTC and, for the first time, we hypothesize an original, hitherto unknown role for AHR in PTC." (PMID 25019383, 2014).
acute pancreatitis (5 papers, 2023 to 2024). An acute inflammatory process that leads to necrosis of the pancreatic parenchyma. "In addition, naringenin has been reported to activate the AhR signal to prevent NLRP3 activation, ultimately protecting against acute pancreatitis-associated intestinal injury." (PMID 39334766, 2024). "The aryl hydrocarbon receptor (AHR) emerges as a critical transcription factor pivotal for the production of IL22, a protective cytokine in acute pancreatitis." (PMID 38612627, 2024). "At the same time, AHR activation by biliverdin, an AHR agonist, increased pancreatic IL22 levels and provided protection against acute pancreatitis." (PMID 38612627, 2024).
anemia (5 papers, 2020 to 2023). A reduction in the number of red blood cells, the amount of hemoglobin, and/or the volume of packed red blood cells. "Overall, this study identified that AhR activation drives abnormal erythrocyte and PLT differentiation in individuals with cancer, and targeting the Kyn–AhR pathway could be explored to treat anemia and thrombocytosis in individuals with cancer." (PMID 37919525, 2023). "Renal anemia is very common in CKD, and indoxyl sulfate could exacerbate anemia by inhibiting hypoxia-inducible factor-dependent erythropoietin production through the activation of AhR." (PMID 35656117, 2022). "It has been reported that activated AhR aggravates renal damage and mediates CKD complications, including cardiovascular disease, anaemia, bone disorders, cognitive dysfunction and malnutrition, and that it influences drug metabolism in individuals with CKD." (PMID 34376166, 2021). "AhR mediates CKD progression and its complications, including cardiovascular disease, anemia, bone disorders, cognitive dysfunction and malnutrition, and it affects the drug metabolism of individuals with CKD." (PMID 33415104, 2020). "This article reviews the current knowledge about the role of AhR in CKD, showing that AhR mediates CKD complications, including cardiovascular disease, anemia, bone disorders, cognitive dysfunction and malnutrition, and that it influences drug metabolism in individuals with CKD." (PMID 33415104, 2020).
brain injury (5 papers, 2016 to 2024). Acute and chronic (see also brain INJURIES, CHRONIC) injuries to the brain, including the cerebral hemispheres, CEREBELLUM, and brain STEM. "Regulation of AhR expression in the brain depends not only on internal stimuli, but also on external stimulation such as traumatic brain injury (TBI) or strokes." (PMID 36232555, 2022). "Our results warrant future studies of the AhR function in brain trauma." (PMID 27506546, 2016). "Therefore, KYN can act as an endogenous ligand that might activate AhR and subsequently induce, at least in part, ischemic brain injury." (PMID 33804845, 2021).
cardiomyopathy (5 papers, 2014 to 2023). A disease of the heart muscle or myocardium proper. "First reported in the late 1990s, AHR−/− mice spontaneously developed mild cardiomyopathy and slight fibrosis as they aged." (PMID 37450589, 2023). "Since cardiomyopathy and vascular hypertrophy are both documented phenotypes of AHR-null mice, a rational biological backdrop for AHR involvement in their regulation exists." (PMID 25467400, 2014). "Additionally, they found that plasma samples from patients with active RRMS exhibit higher global AhR agonistic activity than those from RRMS-remitting individuals, similar to our observations between the groups with Severe and Mild cardiomyopathy." (PMID 38283348, 2023). "Interestingly, when analyzing the CCC group based on the presence of Mild or Severe cardiomyopathy, the Severe CCC patients exhibited significantly higher levels of AhR agonistic activity compared to the Mild CCC patients." (PMID 38283348, 2023). "However, a negative trend was observed between the levels of AhR agonistic activity and the presence of cardiomyopathy." (PMID 38283348, 2023).
Cerebral ischemia (5 papers, 2019 to 2025). Restriction of arterial blood supply to the brain associated with insufficient oxygenation to support the metabolic requirements of the tissue. "The AhR is widely recognized as a potent regulator of inflammation, and its deficiency can lead to a dysregulated inflammatory response; however, in the acute phase of cerebral ischemia, our data suggests its absence mitigates the production of key pro-inflammatory cytokines." (PMID 41452851, 2025). "The first part of this work showed severe nuclear alterations in neurons of the CA1 of AhR+/+ mice after brain ischemia and, to a lesser extent, in AhR-/- ischemic mice." (PMID 41452851, 2025). "In this study, the elevation of hippocampal nNOS levels found in AhR+/+ mice compared with the AhR-/- mice after brain ischemia agrees with a previous report." (PMID 41452851, 2025). "Neuronal AhR activation after cerebral ischemia inhibits CREB signaling and pro-survival pathways subsequently activated by CREB, such as increased expression of brain-derived neurotrophic factor and bcl-x." (PMID 33804845, 2021). "Here, we demonstrate that the nestin+-cell-specific AHRcKO and the pharmacological inhibition of AHR protect sensorimotor and memory deficits against acute cerebral ischemia and exert regulatory effects on anti-inflammation and adult neurogenesis." (PMID 31606043, 2019). "Previous studies have reported that AhR nuclear translocation differs among neurons, astrocytes, and microglia, driving distinct transcriptional programs that influence both inflammatory responses and neuronal injury in models of cerebral ischemia." (PMID 41452851, 2025). "The most remarkable finding of this study is that the absence or the blockade of the AhR reduced the progression of the damage caused by brain ischemia since the absence of the AhR prevents the activation of harmful signaling in the hippocampus." (PMID 41452851, 2025). "Mechanistically, activation of the AHR signaling during cerebral ischemia may mediate specific pathological effects by inhibiting the cAMP response element-binding protein (CREB) signaling pathway." (PMID 36032153, 2022). "Brain ischemia significantly reduced the number of synapses in the dendritic layer of CA1 both in AhR+/+ and AhR-/- ischemic groups; interestingly, a significant difference emerged between control and ischemic animals." (PMID 41452851, 2025).
emphysema (5 papers, 2021 to 2025). "We have previously shown that loss of AhR in mice leads to airspace enlargement, analogous to the emphysema component of COPD, concomitant with unrelenting neutrophilic inflammation in response to cigarette smoke exposure." (PMID 40960917, 2025). "Although we speculate that the ability of the AhR to prevent formation of MNGCs contributes to suppression of the emphysema-like phenotype, a limitation of our study is that we did not directly address whether MNGCs contribute to smoke-induced lung damage." (PMID 35295140, 2021). "The expression correlation between AHR, LRIG1, and EGFR was examined in normal, emphysema, and chronically inflamed lung tissues (emphysema and chronic bronchitis are typical symptoms of COPD)." (PMID 34576152, 2021). "Contrarily, the AHR and EGFR were poorly expressed in emphysema and chronic bronchitis lung tissues but were dominantly found in epithelial cells of normal lung tissue." (PMID 34576152, 2021).
herpesvirus infection (5 papers, 2021 to 2025). "This suggests that the fibroblast (TDO2)/DC (AHR) axis plays a crucial role in herpesvirus infection." (PMID 38680494, 2024). "Specifically, we observed that AHR+CD103+ DCs accumulate in the lungs following BMT in response to herpesvirus infection and respond to increased levels of the AHR ligand kyn, resulting in a skewing of the DCs toward a pro-Th17 phenotype." (PMID 33491663, 2021). "In addition, recent evidence indicates that some agonists of AhR might improve the host response to a herpesvirus infection." (PMID 35056637, 2022). "linc-AhRA is activated by aryl hydrocarbon receptor (AhR) and restricts I-IFN production in microglia upon neurotropic herpesvirus infection and innate immune stimulation." (PMID 34646390, 2021).
inflammatory breast carcinoma (5 papers, 2018 to 2024). An advanced, invasive breast adenocarcinoma characterized by the presence of distinct changes in the overlying skin. "Clinically, high AhR expression in inflammatory breast cancer correlates with lymph node metastases and advanced tumor grade." (PMID 38339226, 2024). "This was documented in tumor tissue from patients with inflammatory breast cancer demonstrating a constitutive overexpression of AhR." (PMID 37232717, 2023). "The AhR signaling pathway elevates the expression of β-catenin and of Wnt5a/b in the tumor tissue of patients with inflammatory breast cancer (IBC) that overexpresses AhR and its target gene/protein CYP1B1." (PMID 37232717, 2023). "AHR inhibition or knockdown/knockout consistently reduced human ER−/PR−/Her2− and inflammatory breast cancer cell invasion, migration, and metastasis." (PMID 29735912, 2018).
kidney injury (5 papers, 2015 to 2023). Trauma to the kidney. "Consistent with our current findings, AhR activation downregulates IRF1 and HIF-1α via miR-142a, which decreases M1 macrophage polarization, increases M2 macrophage polarization, and reduces pro-inflammatory cytokine levels to ultimately protect against CaOx nephrocalcinosis-mediated kidney injury." (PMID 33204326, 2020).
malaria (5 papers, 2020 to 2025). Malaria is a serious and sometimes fatal disease caused by a parasite that commonly infects a certain type of mosquito which feeds on humans. "While global loss of AHR causes aberrant immune responses, we observed that AHR is dispensable in radiosensitive cells during malaria; instead, AHR in Tek-expressing radioresistant cells is required to control parasites and plasma heme, preventing AKI and death." (PMID 33021470, 2020). "AhR signaling plays a critical role in malaria by maintaining the equilibrium between infection cell proliferation, immune response, and inflammation." (PMID 38680494, 2024). "AhR knockout mice were more susceptible to malaria and developed high plasma heme levels and AKI during malaria, suggesting that AhR limits renal damage during malaria." (PMID 38491448, 2024). "We find that AHR ligands are most abundant during acute sickness and demonstrate that AHR signaling is an essential host protection mechanism to regulate plasma heme, limit kidney damage, and promote survival during malaria." (PMID 33021470, 2020). "To more broadly test the role of AHR in the cellular immune response to malaria, we generated bone marrow chimeric mice." (PMID 33021470, 2020). "Recent findings suggest that IDO1-catabolized tryptophan-derivedmetabolites activate the aryl hydrocarbon receptor (AhR) and promoteregulatory T cells in P. vivax infection, providing further insights into the functionalroles of tryptophan metabolism in malaria." (PMID 41180073, 2025). "We conclude that the loss of AHR leads to increased heme release during malaria, but not impaired heme metabolism or increased heme sensitivity." (PMID 33021470, 2020). "Due to the intimate interactions between parasites and the endothelium, we hypothesized that AHR may be required in endothelial cells during malaria." (PMID 33021470, 2020). "Our findings identify a role for AHR in limiting tissue damage during malaria." (PMID 33021470, 2020). "Our metabolomics data suggested that AHR signaling during malaria could be activated by tryptophan and/or heme metabolites." (PMID 33021470, 2020). "After observing that host-derived AHR ligands increase in concentration during acute infection, we demonstrated that AHR is critical in endothelial cells to limit parasitemia and control tissue damage during malaria, in addition to its better-established roles in immune cells." (PMID 33021470, 2020). "In the absence of AHR, mice are more susceptible to a variety of infections and inflammatory insults, including Plasmodium berghei ANKA, a rodent malaria parasite that causes lethal cerebral malaria." (PMID 33021470, 2020).